CD47 (CD47 molecule)
Diseases named in the same sentence as CD47 in open-access papers (continued):
Sharing a sentence is not in itself a finding about the gene and the disease.
anemia (continued). "Preclinical studies have shown that while anti-CD47 antibodies can trigger increased phagocytosis of tumor cells, they can also induce phagocytosis of red blood cells (RBCs), eliciting phagocytic anemia." (PMID 40078999, 2025). "These preclinical results establish maplirpacept as an effective CD47 blocker that mitigates the potential for anemia in patients." (PMID 40078999, 2025). "Higher rates of anemia, a known on-target effect of CD47 blockade, were observed but managed with supportive care." (PMID 41303525, 2025). "Previous generations of CD47 blockers such as anti-CD47 mAbs bind to CD47 on RBCs and elicit anemia." (PMID 40078999, 2025). "CD47 is expressed on various cells such as RBCs and platelets and therapies targeting CD47 can lead to their phagocytosis, resulting in anemia and thrombocytopenia respectively." (PMID 39039207, 2024). "A challenge in translating MAG into the clinic is its side effects, especially anemia due to CD47 expression on erythrocytes." (PMID 38992659, 2024). "Letaplimab is another traditional humanized anti-CD47 monoclonal antibody that has certain antitumor effects but inevitably leads to anemia." (PMID 38464520, 2024). "CD47 is also widely expressed on normal cells, raising concerns about potential anemia and other side effects due to the removal of healthy cells." (PMID 38881902, 2024). "The clinical findings indicated that some cancer patients treated with anti-CD47 experienced anemia symptoms, due to the CD47 expression in red blood cells (RBCs)." (PMID 39588148, 2024). "They found that CD47-/- RBCs were cleared very rapidly in wild mice, and that CD47-/- aggravated anemia in CD47-/-C57BL/6 mice." (PMID 38164142, 2024). "The prevalent expression of CD47 on human erythrocytes and platelets presents a significant challenge, as its inhibition can lead to adverse effects including severe anemia and thrombocytopenia." (PMID 38881902, 2024). "Grade 3–4 treatment-related adverse events occurred in 18% of patients, with the most common being thrombocytopenia, neutropenia, and anemia, consistent with high levels of CD47 expression on platelets, neutrophils, and RBCs, respectively." (PMID 37958404, 2023). "Since SIRPα expression is mainly on macrophages and GS‐0189 does not have a functional Fc, it was theorized that GS‐0189 would result in less anemia compared to most CD47‐targeting agents." (PMID 37206279, 2023). "In clinical trials of CD47 blockade, anemia was a common toxicity observed, with a drop in hemoglobin (Hb) levels after dosing requiring RBC transfusion in patients." (PMID 38125492, 2023). "Our study in a transgenic mouse model reproduces this on-target effect and yields further insights into the mechanism of anti-CD47-induced anemia." (PMID 37095207, 2023). "For other CD47 BsAbs, because the CD47 antibody itself combines with red blood cells, IgG1 cannot be selected; otherwise, it will have severe anemia toxicity." (PMID 36575242, 2023). "Nevertheless, hematotoxicity, especially anemia, has become the most common adverse effect of the CD47 monoclonal antibody." (PMID 36726125, 2023). "Further, various side effects such as anemia, hemagglutination, and chills were observed in many patients that received anti-CD47 therapies." (PMID 36650558, 2023). "The most frequently encountered toxicity was the anticipated on-target anemia, which arises as a pharmacodynamic effect resulting from the blockade of CD47." (PMID 38125492, 2023). "Strategies such as priming doses and next-generation anti-CD47 antibodies with reduced binding to RBCs aim to mitigate treatment-related anemia and minimize on-target adverse effects." (PMID 38125492, 2023). "Targeting the immune checkpoint CD47 or blocking the CD47-SIRPα axis can effectively eliminate glioma cancer cells but also brings side effects such as anemia." (PMID 37063864, 2023). "Presumably, Mdcs play a crucial role in this process and determine the severity of anemia in anti-CD47 treated patients." (PMID 37095207, 2023).
anemia (continued). "Anemia was also detected in mice treated with CD47 antibodies, which is consistent with other findings." (PMID 36435797, 2022). "For humanized IgG2 anti-CD47 mAb, AO-176 preferentially binds integrin-β1 expressed tumor cells with a lower affinity to red blood cells, and treatment-related anemia of any grade was 22%." (PMID 36439116, 2022). "Due to the broad expression of CD47, side effects such as anemia, neutropenia and thrombocytopenia were frequently observed in clinical trials." (PMID 35884427, 2022). "Because of the high expression of CD47 in erythrocytes, the major side effect of clinical application of anti-CD47 antibodies and CD47-targeting SIRPα-Fc fusion protein is anemia due to CD47-mediated phagocytosis of erythrocytes." (PMID 36274066, 2022). "For anti-CD47 mAbs, the most common toxicities included grade 1-2 fatigue (27.2%), headache (21.0%), anemia (20.5%), and IRR (17.6%)." (PMID 36439116, 2022). "STI-6643 had no significant on-target/off-tumor toxicities and a good PK profile without needing low-dose priming sometimes required for competitor antibodies to mitigate the anemia and reduce CD47 expression on circulating erythrocytes." (PMID 35664753, 2022). "For anti-CD47 mAbs, the most common toxicities included grade 1-2 fatigue (27.2%), headache (21.0%), and anemia (20.5%)." (PMID 36439116, 2022). "A priming dosage of the SIRPα-CD47 blocker or choosing the Fc domain of the anti-CD47 mAb to limit interactions with the phagocyte Fc receptor are currently being tried as strategies to reduce RBC phagocytosis and the associated anemia." (PMID 36135216, 2022). "Ingram and colleagues reported that systemic toxicity including severe anemia and even death in treated mice is induced in response to the anti-CD47 nanobody infused with a IgG2a Fc." (PMID 35837100, 2022). "For example, TTI-621 exhibited minimal impact on human erythrocytes, resulting in a lower incidence of anemia than that reported in a phase I study of combinatory treatment of humanized anti-CD47 antibody and rituximab (13% vs 41%)." (PMID 35769486, 2022). "An important concern when using CD47-targeting therapeutics is binding to erythrocytes and their potential elimination, which can lead to anemia." (PMID 35287686, 2022). "Given the ubiquitous expression of CD47, mAbs targeting CD47 have a high “drug sink” on erythrocytes, platelets, and other CD47-expressing cells, leading to anemia and thrombocytopenia." (PMID 36429020, 2022). "Because CD47 is ubiquitously expressed, particularly in hematopoietic cells, consideration of on-target side effects such as anemia and thrombocytopenia have been central to inhibitor development." (PMID 36439116, 2022). "Anemia is the most common adverse event after treatment with CD47-blocking drugs due to the broad expression of CD47 on red blood cells and platelets." (PMID 35837100, 2022). "Since one of the most obvious toxicities associated with CD47-targeting antibodies is the partial depletion of RBCs leading to anemia, we compared the binding ability of anti-CD47 clones STI-6643 and Hu5F9 to RBCs isolated from different species." (PMID 35664753, 2022). "Although SIRPαFc binds less to CD47 on human erythrocytes than the anti-CD47 antibody, the SIRPαFc-related anemia, thrombocytopenia, and neutropenia still happened in clinically enrolled subjects, thus raising a safety concern." (PMID 35422796, 2022). "Since CD47 is ubiquitously expressed, potential problems with anti-CD47 antibodies as anticancer agents were possible off-target effects such as anemia." (PMID 34305918, 2021). "Major concerns regarding the use of CD47-targeted agents are driven by the ubiquitous expression of CD47, which leads to rapid drug elimination, “antigen sink” and hematologic toxicity, such as anemia and thrombocytopenia." (PMID 34944850, 2021).
anemia (continued). "Assuming that CD47 is upregulated in both tumour cells and erythrocytes and platelets, it is understandable that targeting CD47 leads to side effects, including anaemia." (PMID 33430146, 2021). "TTI-621 exhibits minimal binding to human erythrocytes, which reduces the potential for anemia, thereby differentiating it from other CD47 blocking antibodies." (PMID 34717705, 2021). "The potential adverse events using anti-CD47 antibodies as cancer therapeutics include anemia and thrombocytopenia." (PMID 34717705, 2021). "The most serious side effects reported from CD47-targeting agents in clinical trials are anaemia and thrombocytopenia." (PMID 34579739, 2021). "Preclinical data also suggested that TTI-621 was less likely to evoke anaemia when compared to other anti-CD47, thanks to its low erythrocyte–binding profile." (PMID 33430146, 2021). "Anemia is a common reported side effect for humanized Ab Hu5F9 against CD47 used to treat patients with various solid and blood tumors." (PMID 34591795, 2021). "Due to the unselected inhibition of CD47, the administration of anti-CD47 antibody leads to a mild anemia as a result of increased red blood cells attack by phagocytic cells." (PMID 32882841, 2020). "Potential problems with CD47 blockade include anaemia and thrombocytopaenia due to the high expression of CD47 on erythrocytes and platelets." (PMID 32937961, 2020). "An alternative would be to target CD47, but it has been shown on multiple occasions that CD47 antibodies can induce anemia and thrombocytopenia in mice and cynomolgus monkeys due to the high expression of CD47 on erythrocytes." (PMID 32025850, 2020). "Hematological toxicities including thrombocytopenia and anemia are observed in patients treated with anti-CD47 antibodies capable of triggering FcγR-dependent effector functions." (PMID 33256806, 2020). "In summary, mitigating the on-target anemia observed with CD47 blockade is critical to successful clinical development of CD47 targeting agents." (PMID 32038992, 2019). "The main issues with CD47 blockade are healthy cells toxicity (anemia) and antigen sink due to the ubiquitous expression of CD47." (PMID 31544819, 2019). "Here, we investigated the expression of CRPs and CD47, distinguishing uninfected and infected RBCs, in patients with P. falciparum and P. vivax infection with different degrees of anemia from a cohort in Papua, Indonesia." (PMID 30429373, 2018). "We compared CRPs and CD47 expression on infected and uninfected RBCs in adult patients with vivax and falciparum malaria and different anemia severities from Papua, Indonesia." (PMID 30429373, 2018). "A drawback of the anti-CD47 monoclonal antibody treatment is that CD47 blockade can lead to anemia due to rapid depletion of red blood cells." (PMID 28515726, 2017). "Nevertheless, with the exception of studies with CD47-deficient mice and Rhnull individuals, those addressing a relationship between RBC CD47 and anemia are limited." (PMID 28018860, 2016). "This connection between CD47, nRBC and anemia was also confirmed in a study with wild type mice infected by P. yoelii 17XNL that found a decline in the number of nRBCs expressing high levels CD47 when RBC counts were falling." (PMID 28018860, 2016). "The anti-CD47 therapy is associated with transient anemia, fatigue and no severe non-hematologic toxicities." (PMID 40529368, 2025). "When administered systemically, CD47-blocking agents are limited by on-target, off-tumor specificity due to the ubiquitous expression of CD47, especially on red blood cells, which has resulted in adverse side effects such as anemia." (PMID 41322194, 2025). "Thus, these preclinical results establish maplirpacept as an attractive CD47 blocker that mitigates the potential for anemia in patients." (PMID 40078999, 2025). "The binding of CD47 blockers to RBCs may not only lead to anemia but can interfere with pre-transfusion blood testing." (PMID 40078999, 2025).
anemia (continued). "The variation in the expression of the CD47 marker was also observed among smokers with non-hereditary blood diseases such as iron deficiency anemia and polycythemia." (PMID 40587754, 2025). "However, this therapeutic mechanism also targets CD47 molecules on the surface of RBCs, inducing phagocytosis-mediated destruction and resulting in anemia during clinical use." (PMID 40578556, 2025). "However, since CD47 is also widely expressed on normal cells, systemic blockade of CD47 often leads to adverse effects such as anemia." (PMID 41280655, 2025). "However, red blood cells are an exception due to gain of prophagocytic signals with aging, and on-target anemia has frequently been observed with certain anti-CD47 agents." (PMID 41171165, 2025). "Thus, phagocytic anemia was one of the most adverse events in patients receiving CD47-targeting agents, and neutropenia and thrombocytopenia were also frequently observed." (PMID 40402266, 2025). "Therefore, an initial ‘priming’ dose of magrolimab (anti-CD47 mAb) has been proposed to assess anemia before proceeding to higher doses." (PMID 38322418, 2024). "Therefore, CD47-targeting monospecific agents have poor pharmacokinetic characteristics because of their target-mediated drug disposition and toxic effects, such as anemia." (PMID 38983860, 2024). "After receiving anti-CD47 antibodies, senescent erythrocytes acquire CD47 blockade in the presence of enhanced prophagocytic signals, leading to accelerated clearance and ultimately to anemia." (PMID 38464520, 2024). "However, the widespread expression of CD47 in nontumor cells poses challenges, as targeting CD47 can lead to blood toxicity, including agglutination and anemia, hindering the clinical advancement of CD47 monoclonal antibodies." (PMID 39379603, 2024). "Lemzoparlimab, a novel anti-CD47 antibody, did not cause severe anemia to develop when it mediated the phagocytosis of tumor cells." (PMID 38464520, 2024). "However, this strategy has a defect: because of the ubiquitous expression of CD47 on red blood cells, anti-CD47 therapy can also lead to transient anemia." (PMID 36960057, 2023). "However, anemia and thrombocytopenia appear to be formidable challenges since CD47 is ubiquitously expressed on erythrocytes." (PMID 36882399, 2023). "In clinical trials, anemia is the most common adverse effect of blocking the CD47/SIRPα pathway." (PMID 37138855, 2023). "Anemia is the most frequent adverse event reported in patients treated with anti-CD47 antibodies." (PMID 37095207, 2023). "Collectively, as a CD47xCD20 mAb trap, IMM0306 will not cause serious anemia side effects because the receptor segment bound to CD47 does not bind to red blood cells." (PMID 36575242, 2023). "Second, given the ubiquitous expression of CD47 in normal tissues, anti-CD47 antibodies may elicit severe side effects such as anemia, thrombocytopenia, and leukopenia, as observed in animal models." (PMID 36413402, 2023). "Antagonizing CD47 via antibodies with nonspecific delivery was associated with serious side effects, inducing anemia and thrombocytopenia, albeit with potent antitumor efficacy." (PMID 38138963, 2023). "As a result, anemia monitoring and mitigation will be an important part of anti-CD47 treatment." (PMID 37373873, 2023). "While SIRP/CD47 inhibition causes the phagocytosis of tumors, red blood cells (RBC) are also prone to phagocytosis that is dose-dependent and may result in anemia and complications due to infusions." (PMID 37510993, 2023). "However, in clinical trials, anemia and thrombocytopenia have become the dose-limiting toxicity of CD47 because it is also involved in the clearance of red blood cells (RBCs) in the human body." (PMID 37171006, 2023). "A potential approach to address this issue is to reduce the binding of CD47 to RBCs, which could potentially ameliorate anemia and improve the safety profile of CD47-targeting treatments." (PMID 38125492, 2023).
anemia (continued). "As a consequence of the relatively high expression of CD47 on RBCs and platelets, hematotoxicity—which includes anemia, thrombocytopenia, hemagglutination, and neutropenia—has been a major concern among the various side effects observed in clinical studies of anti-CD47 therapies." (PMID 36650558, 2023). "Although it was claimed that such a level of anemia can be relieved by supportive care and blood counts can return to normal within 2–3 weeks, prevention of anemia has been the key focus of toxicity management after anti-CD47 therapy." (PMID 36123348, 2022). "Notably, targeting CD47 induced hematotoxicity including anemia and thrombocytopenia due to the off-target effect on the blocking of CD47 expressed on surface of platelets and erythrocytes." (PMID 35769486, 2022). "However, due to ubiquitous expression of CD47, the antigen sink and hematologic toxicity, such as anemia and thrombocytopenia, are main problems for developing CD47-targeting therapies." (PMID 35256517, 2022). "However CD47 is widely expressed on virtually all cells in the body, and, particularly, hematologic adverse events are often observed in patients treated with anti-CD47 mAbs, e.g., anemia, thrombocytopenia, lymphopenia, and neutropenia." (PMID 35884427, 2022). "However, the major limitation of anti-CD47 antibody-based therapy is dose-dependent phagocytosis of RBCs, leading to severe anemia in patients." (PMID 36135216, 2022). "The main side effect of anti-CD47 antibody therapy is anemia (a decrease in the number of red blood cells), as the high level of CD47 protein expression on the surface of red blood cells (RBCs) prevents them from preterm elimination; conversely, RBCs under CD47 therapy get consumed." (PMID 35118420, 2022). "As most anti-CD47 antibodies cause anemia due to phagocytosis of RBCs, Lemzoparlimab was generated to specifically target CD47 on malignant cells while not recognizing CD47 on RBCs, due to unique CD47 binding properties." (PMID 35884427, 2022). "Thus, anemia is one of the main side effects of anti-CD47 therapy observed in 89% of patients in a phase 1 trial of magrolimab in patients with acute myelocytic leukemia (AML)." (PMID 36429020, 2022). "Many of the monoclonal anti-CD47 agents currently developed target different epitopes and as a result, a specific subset has been found to only weakly bind to red blood cell CD47 (lemzoparlimab, magrolimab, and AO-176), allowing them to spare these cells and prevent the development of anemia." (PMID 36031601, 2022). "The occurrence of anemia was expected, as it is an on-target effect of anti-CD47 antibody therapy." (PMID 35884427, 2022). "However, a complication of effective targeting of the ubiquitously expressed CD47 with antibodies or fusion proteins containing an Fc is the occurrence of side effects such as anemia and thrombocytopenia." (PMID 34917090, 2021). "However, anti-CD47 therapy should be used with caution, as both anemia and thrombocytopenia have been observed in human trials of anti-CD47 therapeutics." (PMID 33572846, 2021). "However, due to CD47 ubiquitous expression, antibody blockade interferes with important physiological roles of the receptor, therefore promoting adverse events such as anemia, thrombocytopenia and splenomegaly." (PMID 34638503, 2021). "Given that CD47 is ubiquitously expressed by normal of the hematopoietic system such as RBCs and platelets, potential adverse events using anti-CD47 antibodies as cancer therapeutics include anemia and thrombocytopenia." (PMID 32677994, 2020). "However, there are a series of biosafety problems with such treatments including anemia, and preclinical studies have demonstrated different effects of CD47-targeted drugs on different tumor types." (PMID 32082311, 2020). "This is due to CD47 high expression on RBCs, especially aged RBCs and blockade of CD47 on RBCs can lead to their phagocytic removal by macrophages, which eventually induced anemia and hemagglutination." (PMID 31931812, 2020).